CCL2 (C-C motif chemokine ligand 2)
Diseases named in the same sentence as CCL2 in open-access papers (continued):
Sharing a sentence is not in itself a finding about the gene and the disease.
tumor (continued). "CCL2 has been reported to bind its receptors CCR2 and CCR4 on lymphocytes, resulting in recruiting immune cells to tumor sites, which causes immunosuppression." (PMID 31207928, 2019). "Tumor derived CCL2 has also been correlated with greater CCR2-expressing T cell trafficking in several different solid tumors." (PMID 30736355, 2019). "Tumor cell-conditioned myeloid suppressor cells were shown to produce CCL2 and CXCL16, which enhanced angiogenesis." (PMID 31527616, 2019). "CCL2 secreted by tumor cells is well known to be a crucial chemokine factor for immature monocyte recruitment and associated with poor prognosis, whereas its absence is associated with increased survival in cervical cancer patients." (PMID 31861892, 2019). "Given that bone marrow-derived macrophages (BDMs) are recruited to the tumor by chemokine (C–C motif) ligand 2/CCL receptor 2 (CCL2/CCLR2) or colony-stimulating factor-1 (CSF-1)/CSF-1R axis, inhibitors targeting these ligands and receptors have been developed." (PMID 30823602, 2019). "These TDFs are key mediators in the crosstalk between monocytes and tumor cells and include colony-stimulating factor-1 (CSF-1), several C−C chemokine ligands, such as CCL2, also known as MCP-1 and VEGF." (PMID 31878087, 2019). "Summarizing, this paragraph points toward a tumor-promoting, immunosuppressive role of CCL2 in the tumor microenvironment." (PMID 31921102, 2019). "This positive feedback loop can help explain the efficacy of CCL2 blockade in anti-tumor response as shown by previous groups." (PMID 31396227, 2019). "Monocytes, known for their functional and molecular plasticity, can be recruited to the tumor site by tumor‐secreted chemo‐attractants (eg, CCL2, S100A8/S100A9), and polarized toward M1 or M2 macrophages depending on the cytokine milieu." (PMID 31033233, 2019). "The C–C chemokine ligand type 2 and receptor (CCL2/CCR2) pathway is required for the mobilization of monocytes from the bone marrow into the tumor microenvironment." (PMID 31540435, 2019). "Stromal production of immunosuppressive chemokines CCL2, which promote tumor metastasis and M2 macrophage recruitment, have also been described." (PMID 31921140, 2019). "Consistent with pathological features, there was significantly higher expression of cytokines IL-6 (Il6) and TNFα (Tnfa), chemokines KC (Cxcl1), MIP2 (Cxcl2), and MCP1 (Ccl2), and tumor-promoting molecule COX2 (Cox2) in Nlrp12-/- HCC." (PMID 30990169, 2019). "Other mechanisms for diminishing TAM recruitment by the tumor or re-polarizing TAMs to the M1 phenotype are also being investigated, including antagonism of CCL2 and/or CCL5 or their receptors." (PMID 31921140, 2019). "TANs are known to secrete multiple growth factors and chemokines such as TNFα, CCL2, IL-8, and IL-17a into the tumor microenvironment, where they promote the growth and invasion of the underlying tumor by triggering multiple pathways." (PMID 30616627, 2019). "Along this line, various tumor cells transfected to express CCL2 were significantly lysed by PEMs treated with LPS, whereas parental (untransfected) or control cells (transfected with control complementary DNA) were not." (PMID 31921102, 2019). "Apart from the molecular aspects of CCL2 biology, the tumor microenvironment is highly complex, and a multitude of molecules and cell types impact on the tumor vs. host-defense battle." (PMID 31921102, 2019). "Both IL-6 and CCL2 play a major role in promoting tumorigenesis by altering the primary tumor immune microenvironment and enhancing a more aggressive primary tumor phenotype." (PMID 30458886, 2018). "Of note, CCL2 stimulates tumor cell proliferation and migration by activating IP3-dependent Akt/PKB signal pathway." (PMID 29458367, 2018). "CCL2 inhibition in combination with docetaxel has shown increased efficacy, compared to docetaxel treatment alone, resulting in decreased tumor growth and metastatic spread in prostate cancer." (PMID 30356656, 2018).
tumor (continued). "CCL2 induces accumulation and suppressive function of myeloid derived suppressive cells in tumor microenvironment in STAT3-dependent manner." (PMID 29541413, 2018). "CCL2 is a member of the C-C chemokine family and involved in the tumorigenesis and metastasis of tumor by participating in mediating the tumor microenvironment." (PMID 29458367, 2018). "Further noteworthy outcomes of the Notch/CCL2 axis are important in the nasty communication between tumor cells and BMSCs in the primary tumor site and in the metastatic one." (PMID 30154786, 2018). "A significantly stronger induction of CXCL8 and CCL2 was observed in our tested tumor cells as compared to HEK." (PMID 30266096, 2018). "The activation of chemokine receptor CCR2 in MSCs interacting with irradiated 4T1 cells was also observed, as well as higher expression of MCP-1/CCL2 in the tumor parenchyma of 4T1 mice." (PMID 29615915, 2018). "CCL2 is the most cancer-involved member of the CC chemokine family, and its high expression in the tumor tissue promotes tumorigenesis and metastasis." (PMID 30059519, 2018). "CCL2 expression was markedly correlated with tumor status (P = 0.004), lymph node metastasis (P = 0.007) and TNM stage (P = 0.026)." (PMID 29934505, 2018). "The profound tumor microenvironment remolded by estrogen and chemokines like CCL2 shed light on new therapeutic regimes for hormone-dependent breast cancer." (PMID 29934505, 2018). "CCL2 and its receptor (CC chemokine receptor, CCR2) are pro-inflammatory mediators and chemoattractant that regulate the development and progression of tumor through migration and infiltration of monocytes or TAMs and CCL2/CCR2 axis." (PMID 29458367, 2018). "Tumor-derived chemokine CCL-2 is a monocyte-chemotactic protein and its high level correlates with increased numbers of TAMs in tumor tissue and a poor prognosis." (PMID 28660349, 2018). "We further demonstrate that this is associated with increased CCR2 expression by KLRG1+ NK cells from Ackr2−/− mice and attendant hyperresponsiveness of these cells to tumor-expressed CCL2." (PMID 30158126, 2018). "Monocytes are recruited to sites of tumor growth in response to chemoattractants released by tumor cells, such as colony stimulating factor 1 and the chemokine C-C motif chemokine ligand 2 (CCL2), where they differentiate into macrophages." (PMID 29765907, 2018). "GB EVs modulate NHAs by increasing their migratory capability and inducing the cytokine production (as ILs 4, 10, and CCL2), which consequently stimulate the tumor growth." (PMID 30123112, 2018). "In these models, circulating tumor-derived microparticles entered the lung parenchyma readily and were taken up by both AMs and IMs, which subsequently produced CCL2." (PMID 30597969, 2018). "A substantial portion of TAMs are derived from CCR2-expressing circulating classical monocytes, which migrate to the tumor sites under the guidance of tumor cell-derived CCL2." (PMID 30597969, 2018). "Tumor cells express many factors including CCL2 (under hypoxic conditions), M-CSF or GM-CSF, IL-10, TGF-β, and IL-6, all of which favor the recruitment and generation of TAMs." (PMID 29868007, 2018). "In this case, canonical Notch signaling directly regulates the expression of CCL2 and IL-1β, leading to the adhesion of monocytes to blood vessel and extravasation to migrate toward tumor tissue." (PMID 29686671, 2018). "Several studies have shown that the CCL-2 is used to recruit monocytes into an immunosuppressive tumor microenvironment." (PMID 28660349, 2018). "Increased CCL2 in serum recruits both monocytic myeloid-derived suppressor cells and macrophages to the tumor site, thereby increasing tumor metastasis." (PMID 30086763, 2018). "Other approaches such as monoclonal antibody therapy against CXCR2, CCL2, or IL-18 to inhibit MDSCs trafficking into tumors also successfully induces tumor regression upon anti-PD1 treatment." (PMID 30619850, 2018).
tumor (continued). "I3C and DIM modulation of androgen receptor mediated pathways can attenuate monocyte migration to tumor cells through CCL2-dependent pathways." (PMID 29364159, 2018). "A correlation between the expression of CCL2 and tumor progression was previously reported, but to the best of our knowledge, the correlation between CCL2 and EC is newly reported here." (PMID 29890681, 2018). "Tumor-derived Jagged, in turn, boosts the expression of IL-1β and CCL2 in the same tumor cells and in TAMs." (PMID 30154786, 2018). "Collectively, these results indicate that CCL2 secreted from both tumor cells and stromal cells plays a pivotal role in the recruitment of monocytes and subsequent accumulation of MAMs in the site of metastasis." (PMID 30483271, 2018). "In the MC38 colon tumor model above, genetic knockdown of CCL2 yielded complete tumor eradication in 60% of irradiated mice further supporting MDSCs as a major driver of immunosuppression." (PMID 30766539, 2018). "Collectively, these results suggest that cancer cells promote TAM accumulation by producing CCL2 via tumor type specific signaling pathways." (PMID 30483271, 2018). "An elegant study by the Reedijk group showed that Notch signaling in tumor cells regulates the expression of pro-inflammatory cytokines, IL1β and CCL2, and induced the recruitment of TAM." (PMID 29915603, 2018). "HIF-1α is able to recruit monocytes and macrophages by promoting chemical chemokine 2 (CCL2) secretion, which accelerates the activation of PSCs and enhances tumor progression." (PMID 30455857, 2018). "CCL2 is a chemotactic stimulus for the recruitment of Mo-MDSCs and macrophages that, in turn, induce the metastatic site to sustain the growth of tumor cells that have already colonized the lungs." (PMID 30154786, 2018). "It is known that chemokine CCL2 is released into the tumor microenvironment by endothelial cells and fibroblasts to activate lymphocytes and macrophages." (PMID 30059519, 2018). "A beneficial drug permeability effect of CCL2 or IL-6 must outweigh potential tumor stimulatory pathways." (PMID 30006619, 2018). "Although the total number of recruited macrophages did not change, there was a clear change in the polarization state of TAMs toward a more anti-tumor phenotype after CCL2 blockade." (PMID 30245686, 2018). "CCR2 (the receptor for chemokine CCL2) is expressed on blood monocytes, while CCL2 is synthesized and secreted by both tumor cells and stroma cells." (PMID 29599778, 2018). "CCL2 has been shown to have multiple pro-tumorigenic functions such as mediating tumor growth and angiogenesis." (PMID 30042333, 2018). "This leads to increased recruitment of KLRG1+ NK cells to CCL2-expressing tumors and enhanced tumor killing." (PMID 30158126, 2018). "CCL2 is produced by variety of cell types, not only by tumor cells but also by stromal cells such as monocytes, fibroblasts, and endothelial cells." (PMID 30151375, 2018). "Ectopic expressions of CCL2 both at the mRNA and protein levels are strongly correlated with enhanced infiltration of TAMs at tumor sites and promote tumor aggressiveness in an experimental animal model." (PMID 30619286, 2018). "Preventing recruitment of macrophages to the tumor site has been achieved through targeting macrophage chemoattractants such as CSF-1 and CCL2 or their corresponding receptors: CSF-1 receptor (CSF-1R) and C-C chemokine receptor type 2 (CCR2)." (PMID 30356656, 2018). "Elevated CCL2 within the tumor microenvironment promoted the recruitment of C-C chemokine receptor type 2 expressing (CCR2+) myeloid cell types, including MDSC and TAM." (PMID 30042333, 2018). "Tumor-derived CCL2 recruits different subsets of myeloid cells, including TAMs, which contribute to cancer cell proliferation, the inflammatory microenvironment of the tumor, immune response evasion and angiogenesis." (PMID 30237493, 2018).
tumor (continued). "In this model, genetic deletion of Ccl2 in the Lkb1−/− tumors significantly reduces the number of TAMs, which results in the delayed tumor progression and prolonged overall survival." (PMID 30483271, 2018). "IHC staining results showed positive signals of CCL2 were primarily located in the cytoplasm of tumor cells." (PMID 29934505, 2018). "MCP-1, known as CC-chemokine ligand 2 (CCL2), is a micromolecular potent chemoattractant for leukocytes to gather on the position where tissue is injured and inflammation or tumor are triggered." (PMID 30382864, 2018). "Compared with KLN205 and a metastatic LUAD line (344SQ), LN4K1 secreted abundant levels of CCL2 in vitro, which was confirmed in the plasma of tumor-bearing mice." (PMID 29777108, 2018). "CCL2 mediates the tumor generation and metastasis through multiple mechanisms, such as inducing tumor angiogenesis, mediating tumor immune response, promoting the tumor invasion and metastasis, and directly contributing to tumor progression." (PMID 29458367, 2018). "These tumor types express high levels of CCL2 which have been shown to be responsible for OCL maturation and bone resorption by tumors generated by these cells." (PMID 29930538, 2018). "The concentration of CCL2 in BC increases with advancing tumor stage, while a median level of CCR2 decreases with advancing stage." (PMID 30151375, 2018). "With novel, immunocompetent metastasis models, we demonstrated that tumor cell derived CCL2-mediated recruitment of IMs is necessary and sufficient for LUSC metastasis." (PMID 29777108, 2018). "Further investigation revealed that the deletion of Rbpj in macrophages results in loss of CCR2 and TAM markers, suggesting a cross-talk between canonical Notch signaling and the CCR2/CCL2 signaling pathway in TAMs in the tumor microenvironment." (PMID 29686671, 2018). "Preclinical studies have shown the effectiveness of CCL2 neutralizing antibodies in blocking PC tumor growth in bone both as a single agent and in combination therapy." (PMID 29930538, 2018). "Monocyte chemoattractant protein-1 (MCP-1, also known CCL2) was among the first chemoattractant factors, which has been identified to contribute tumor proliferation and progression." (PMID 30319362, 2018). "CD11b/Gr1mid (a myeloid cell subset) cells are recruited from bone marrow by tumor-derived CCL2 and they increase in number markedly during development of liver metastases." (PMID 29734668, 2018). "In an invasive BC model, the tumor-released chemokine CCL2 and the subsequent IL-1β release from TAMs (see Section 2.8) were shown to induce IL-17 production in γδ T cells." (PMID 30200242, 2018). "The reduction of CXCL8 (and CCL2) was paralleled by impaired tumor angiogenesis and decreased macrophage density both in the in vitro and in vivo models of mice anaplastic thyroid cancer xenograft." (PMID 29977225, 2018). "One of the major consequences of CCL2 expression by BC cells is the recruitment of CCR2 positive myeloid cells to the primary tumor which facilitates metastasis in general." (PMID 29930538, 2018). "IGF-1R inhibition in tumor epithelial cells elevated interleukin (IL)-6 and C-C motif chemokine ligand 2 (CCL2) expression, which was reversed by ROS scavenging." (PMID 30458886, 2018). "CCL2 mRNA levels were at least fourfold higher in 231_HM.LNm5 primary tumour cells compared to the three other lines." (PMID 29720474, 2018). "The increased CCL2 promoted an influx of CD11b+ monocytes into the primary tumor that also had increased matrix metalloproteinase (MMP)-2, MMP-3, and MMP-9 expression." (PMID 30458886, 2018). "We detected significantly higher plasma levels of CCL2 and commonly accepted tumor marker CA 15-3 in the comparison of stages III and IV to stage I (p<0.001) and to stage II (p=0.001)." (PMID 30151375, 2018). "Their influx and positioning in the tumour is mediated by chemokines (e.g., CCL2), growth factors (e.g., CSF1) and complement components." (PMID 29422500, 2018).
tumor (continued). "The chemokine (C-C motif) ligand 2 (CCL2) with its cognate receptor chemokine (C-C motif) receptor 2 (CCR2) plays important roles in tumor invasion and metastasis." (PMID 29934505, 2018). "CCL2 can be produced by bone marrow-derived stromal cells or tumor cells, while tumor cells produce IL-1β." (PMID 29686671, 2018). "One of them asserts that macrophages are derived from circulating monocytes and are recruited to the tumor site by monocyte chemotactic protein-2 (CCL2), a chemotactic factor." (PMID 29361917, 2018). "Tumor-derived factors such as C-C ligand 2 (CCL2) and colony stimulating factor-1 (CSF-1) can also recruit further macrophages to the tumor from the bone marrow (BM) and spleen." (PMID 30459812, 2018). "Studies have demonstrated that many tumor cells can express CCL2, suggesting its role in the course of cancer." (PMID 30382864, 2018). "Tumor‐derived chemotactic factors such as Ccl2, Ccl3, Ccl5, and Ccl7 are known to recruit macrophages to the growing tumor." (PMID 29047229, 2018). "The increase in the number of tumor-infiltrating NK cell in Salmonella-treated group is consistent with the increment in Ccl2, Ccl3, and Ccl5 gene expression observed in these groups, since one function of these chemokines is the recruitment of NK cells." (PMID 29410666, 2018). "Tumor-associated macrophage infiltration is associated with poor prognosis and sustains a cytokine milieu abounding of TGF-β, IL-1β, and CCL2 that collaborate to promote monocytes recruitment and promotes an immunosuppressive TME." (PMID 30154786, 2018). "TAMs contribute to tumor progression also by producing chemokine CCL2, which leads to the elevated angiogenic profile attributed to this chemokine." (PMID 30151375, 2018). "Because it has been reported that the tumour‐derived factors such as CCL2, SDF1, IL6, TNFα, VEGF, G‐CSF, TGFβ, and CXCL1 function in the pre‐metastatic phase, we applied those factors to HepELs in the tumour‐bearing mouse liver in vitro." (PMID 29930175, 2018). "In one study, RNAi-mediated depletion of CCL2 in A549 carcinoma cells prevented osteoclastogenesis in tibias orthotopically injected with these cells and this had a modest effect of tumor cell proliferation within the bone." (PMID 29930538, 2018). "Another ligand, CCL-2, has been found to have the ability to accelerate tumor growth and metastasis of cancer cells upon binding with typical specific receptors." (PMID 30140603, 2018). "Mouse models of other types of solid tumors have also demonstrated that cancer cell-derived CCL2 plays pivotal roles in the accumulation of TAMs, whereas regulatory mechanisms behind CCL2 production differ between tumor types." (PMID 30483271, 2018). "MDSCs generated in the bone marrow migrate into the tumour and peripheral lymphoid organs, mainly attracted by the chemokines CCL2 and CCL5, and receive stimuli that activate their immunosuppressive properties." (PMID 28404796, 2017). "There is sufficient evidence to show that initial release of chemokines such as CCL2, GM-CSF mark a potentially irreversible turning point for tumor infiltration, immunological evasion, and tumor immune support." (PMID 28441391, 2017). "In fact, other investigators have shown CCL2 elevation in the tumor microenvironment and premetastatic niche enhances tumor growth and metastasis." (PMID 28143493, 2017). "Another chemokine implicated in the RT-induced myeloid cell recruitment to the tumor is C-C motif ligand 2 (CCL2)." (PMID 28348554, 2017). "The origin of TAMs is considered to be circulating monocytes, and various chemoattractants, such as C–C motif chemokine ligand 2 (CCL2) or VEGF—which are produced by tumor tissue—lead monocytes to infiltrate into the tumor." (PMID 29286323, 2017). "Pleural disseminated, mutant KRAS bearing tumour cells upregulate and systemically release chemokine ligand 2 (CCL2) into the bloodstream to mobilize myeloid cells from the host bone marrow to the pleural space via the spleen." (PMID 28508873, 2017).